RN7SL104P (RNA, 7SL, cytoplasmic 104, pseudogene)
Gene: Miscellaneous RNA gene on chromosome 2 (15,950,689 to 15,950,981, reverse strand). Ensembl gene ENSG00000243541.
Homologues: Orthologues: chimpanzee Metazoa_SRP (99% identical), macaque Metazoa_SRP (89% identical). Paralogues in human: RN7SL1 (80% identical), RN7SL3 (79% identical), RN7SL2 (79% identical), RN7SL383P (78% identical), RN7SL296P (77% identical), RN7SL664P (77% identical), RN7SL441P (77% identical), RN7SL45P (77% identical), RN7SL464P (77% identical), RN7SL778P (77% identical), RN7SL220P (76% identical), RN7SL408P (76% identical), and 709 more.